TG (thyroglobulin)
Diseases named in the same sentence as TG in open-access papers (continued):
Sharing a sentence is not in itself a finding about the gene and the disease.
lymph node metastasis (continued). "AJCC stage II disease was significantly associated with age ≥55 years, lymph node dissection, angiolymphatic invasion, extrathyroidal extension, lymph node metastasis, number of metastatic lymph nodes, non-low risk of recurrence, first stimulated thyroglobulin, and response to therapy at 1-year." (PMID 40900471, 2025). "The most influential parameters in the model included postoperative thyroglobulin levels, BMI, anti-thyroglobulin antibody levels, TSH levels, tumor size, and lymph node metastasis." (PMID 40282484, 2025). "In this study, we aimed to investigate the predictive value of pre-ablative stimulated thyroglobulin (Tg) and Tg/thyroid-stimulating hormone (TSH) to identify lymph node metastasis (LNM) or distant metastases (DM) prior to radioactive iodine (RAI) treatment." (PMID 30942058, 2019). "There is no alternate ultrasound, neck CT, and thyroglobulin (Tg) methods to assess the occult lymph node metastasis." (PMID 36284638, 2022). "In adults, the combination of neck US and FNAC has been shown to detect cases of lymph node metastasis and local recurrence not found by whole-body scan or serum thyroglobulin determination." (PMID 35900783, 2022). "Although s-thyroglobulin was negative, the mediastinal lymph node metastasis was suspected at this time." (PMID 35777066, 2022). "Although s-thyroglobulin was negative, the most suspected diagnosis of this mediastinal nodule was lymph node metastasis." (PMID 35777066, 2022). "Now there is no better method to assess occult lymph node metastasis other than ultrasound, neck CT, and thyroglobulin (Tg)." (PMID 36284638, 2022).
congenital hypothyroidism (30 papers, 2012 to 2026). A thyroid hormone deficiency present from birth. "Humans bearing mutations impairing any steps leading to thyroglobulin iodination present with congenital hypothyroidism; nevertheless, untreated goitrous patients bearing bi-allelic mutation in thyroglobulin can still make thyroid hormone." (PMID 41979536, 2026). "We described new forms of thyroglobulin gene (TG) mutation resulting in fetal goiter and congenital hypothyroidism in a pendred syndrome (PS) patient." (PMID 41394090, 2025). "In earlier work, we mapped the interactome of the secreted thyroid prohormone thyroglobulin (Tg), comparing the WT protein to secretion-defective mutations implicated in congenital hypothyroidism (CH)." (PMID 39103653, 2024). "THD due to thyroglobulin (TG) gene variants is a cause of congenital hypothyroidism (CH) with a wide clinical spectrum, ranging from mild to severe permanent hypothyroidism." (PMID 39040671, 2024). "In congenital hypothyroidism from biallelic thyroglobulin mutation, thyroglobulin is misfolded and cannot advance from the ER, eliminating its secretion and triggering ER stress." (PMID 33914707, 2021). "The method clarifies how mutant forms of the pro-hormone thyroglobulin result in congenital hypothyroidism by elucidating the defects in protein quality control." (PMID 39103653, 2024). "In our previous studies, we have demonstrated the association of certain variants of the thyroid-stimulating hormone receptor (TSHR), thyroid peroxidase (TPO), and thyroglobulin (TG) genes with congenital hypothyroidism." (PMID 34638176, 2021). "Elevated serum thyroglobulin levels, a normal or increased thyroid uptake or the presence of thyroid gland verified by ultrasound can exclude a diagnosis of congenital hypothyroidism." (PMID 24027558, 2013). "A 21-year-old Japanese man treated with levothyroxine for congenital hypothyroidism had an enlarged thyroid gland with undetectable serum thyroglobulin despite elevated serum TSH level." (PMID 22934199, 2012). "Serum thyroglobulin levels provide information about the etiology of congenital hypothyroidism." (PMID 39857886, 2025). "Transient congenital hypothyroidism, TSH receptor defects, or iodine blockade are diagnosed on the basis of the results of ultrasonographic tests and measurements of serum thyroglobulin levels." (PMID 39857886, 2025). "At that time, the cause of hypothyroidism was not clear, but a markedly elevated serum thyroglobulin concentration argued against a diagnosis of congenital hypothyroidism." (PMID 24027558, 2013). "Among the unsolved familial cases, there was a large family (family A) with 13 individuals with nongoitrous congenital hypothyroidism, five with subclinical hypothyroidism and three with suspected MNG based on high serum thyroglobulin levels." (PMID 38714868, 2024).
breast carcinoma (27 papers, 2009 to 2025). "TG (thyroglobulin) hypermethylation has been associated with aggressive tumor behavior in breast cancer, and CNTLN, hypermethylated within gene bodies in our study, has been detected in epithelial OC cell lines, although its functional role remains unclear." (PMID 40563675, 2025). "The Hardefeldt meta-analysis confirmed this relationship, finding evidence of an increased risk of breast cancer associated with a diagnosis of goiter or the presence of serum thyroid autoantibodies, particularly anti-TPO and anti-TG." (PMID 35111194, 2021). "Relationships between thyroperoxidase antibodies (TPOAb), thyroglobulin antibodies (TgAb) and breast cancer have been previously demonstrated." (PMID 23680448, 2013). "Corresponding signs of thyroid autoimmunity, such as diffuse hypoechogenicity along with the presence of anti-TPOAb and anti-thyroglobulin antibodies, were discovered at higher levels in patients diagnosed with breast cancer in comparison to patients with benign breast disease and healthy controls." (PMID 35111194, 2021). "Metastatic breast carcinoma cells typically exhibit positive expression of mammary epithelial differentiation markers (e.g., GATA, Mammaglobin, ER/PR, TRPS1) and negative expression of thyroid follicular cell markers (e.g., Thyroglobulin, TTF-1, PAX-8)." (PMID 41199830, 2025). "These tests can be completed with CDX2 and CK19 for upper gastrointestinal tract, biliary ducts and pancreas, thyroglobulin for thyroid adenocarcinoma, NY-BR-1 and GATA-3 for female breast cancer, Mel-A, S100 and HMB45 for melanoma, and vimentin and Mel-A for kidney and adrenal gland tumors." (PMID 29116378, 2018). "Additionally, staining for thyroglobulin (TG) and thyroid transcription factor 1 (TTF-1), which are expressed in the thyroid gland but not in breast cancer tissue, was performed to differentiate the thyroid component from neoplastic breast cells." (PMID 23833651, 2013).
COVID-19 (25 papers, 2021 to 2025). A disease caused by infection with severe acute respiratory syndrome coronavirus 2. "In our article, the objective was to evaluate thyroglobulin (TG) levels in patients hospitalized with COVID-19, perceiving TG as a biomarker of thyroid damage." (PMID 36969717, 2022). "Last but not least, a recent study of 72 healthy individuals in Greece showed no clinically significant change in thyroid function, anti-thyroid peroxidase and anti-thyroglobulin antibody titres up to one month after the second dose of mRNA COVID-19 vaccines." (PMID 36229814, 2022). "CSF examination revealed five cases with abnormalities: anti-thyroid antibodies (anti-TG, TRAK, anti-TPO, and anti-TRAb) (#16&#77), COVID-19 (#111), neurosyphilis (#30), and twice OCBs type II and typical white matter lesions on brain MRI, that were diagnosed as multiple sclerosis (#49&51)." (PMID 33785807, 2021).
metastatic disease (25 papers, 2009 to 2026). "It facilitates removal of the residual thyroid tissue/disease, permits screening and ablation of metastatic disease with radioactive iodine, and allows for thyroglobulin level monitoring, thereby eliminating the risk of recurrence of the tumor and prolonging survival." (PMID 27487312, 2016). "To date, some dynamic factors based on changes in blood markers such as thyroglobulin and/or metastatic tumor volumes have been identified, which are helpful for evaluating the disease condition of patients." (PMID 41400051, 2026). "Following total thyroidectomy and radioactive iodine ablation, the elimination of normal thyroid tissue enhances the utility of thyroglobulin as a sensitive marker for residual, recurrent, or metastatic disease." (PMID 40746588, 2025). "To date, the quality of the evidence is too low to identify a unifying threshold thyroglobulin level above which persistent or metastatic disease can be suspected." (PMID 39272954, 2024). "While elevated serum thyroglobulin can be a marker for residual, recurrent, or metastatic disease in DTC, approximately one quarter of these patients have negative radioiodine whole-body scans (WBS)." (PMID 39558957, 2024). "At primary diagnosis, elevated thyroglobulin (TG) level was noted in one patient (7.7%) who had metastatic disease." (PMID 37726744, 2023). "RAI iodine 131 helps in the earlier detection and treatment of metastatic disease; aids in interpreting serum thyroglobulin (Tg) measurements during serial follow-up." (PMID 36407154, 2022). "Striking elevation of serum levels of thyroglobulin, suggesting hidden metastatic disease, was detected 9 years later, and definite confirmation of bone metastasis was performed after another 2 years." (PMID 24616777, 2013). "If neck US is normal, additional imaging such as CT or MRI can be considered to look for distant metastatic disease, especially lung metastases, if thyroglobulin levels suggest the disease may be present at a distant site." (PMID 35900783, 2022). "Chou and colleagues described that, after total or near total thyroidectomy, a non-stimulated thyroglobulin level <2.5 ng/mL might identify patients at low risk for persistent or metastatic disease." (PMID 39272954, 2024). "Negative staining with anti-thyroglobulin and anti-calcitonin antibodies would favor a metastatic tumor." (PMID 26410084, 2015). "Immunohistochemistry demonstrated that these tumor cells were positive for both cytokeratin 7 (CK7) and thyroid transcription factor-1 (TTF-1) and were negative for both CK20 and thyroglobulin, which concords with metastatic disease from lung origin." (PMID 26410084, 2015). "No signs of metastatic disease are present up to date and the levels of thyroglobulin (Tg) are within normal range - respectively < 0.2 ng/ml." (PMID 25810698, 2015). "Additionally, negative staining with anti-thyroglobulin and anti-calcitonin antibodies can be a valuable tool in favoring a diagnosis of metastatic tumor." (PMID 38320308, 2024). "Radioiodine scan may not be reliable to detect brain metastasis from PTC; however, a high serum thyroglobulin level may be helpful but not specific, as it is usually high in all metastatic disease." (PMID 19558727, 2009).
Anxiety (22 papers, 2011 to 2026). Intense feelings of nervousness, tension, or panic often arise in response to interpersonal stresses. "However, we must remember the challenges resulting from these new approaches to TC management, such as long-term follow-up costs, patient and clinician anxiety, and uncertainty in thyroglobulin (Tg) monitoring after nonradical treatment." (PMID 37894308, 2023).
follicular thyroid carcinoma (21 papers, 2009 to 2025). "In 1988, the World Health Organization defined MMFCC as a tumor that displays the morphological features of both medullary and follicular carcinomas with immunoreactivity for calcitonin and thyroglobulin, respectively." (PMID 38647958, 2024). "In follicular thyroid carcinomas, the rhabdoid inclusions are vimentin-positive but lack immunoreactivity for cytokeratins, thyroglobulin, smooth-muscle actin, and desmin." (PMID 29938394, 2018). "Immunohistochemistry revealed positivity for thyroglobulin and thyroid transcription factor 1, consistent with metastatic follicular thyroid carcinoma (FTC)." (PMID 26550511, 2015). "The biopsy of the lesion demonstrated neoplastic cells stained positive for thyroglobulin, thyroid transcription factor-1, and cytokeratin-7, consistent with metastatic follicular thyroid cancer." (PMID 26425617, 2014). "This entity differs from MMFTC, which is defined as a primary tumor showing morphological features of MTC together with immunoreactivity of calcitonin, and the morphological features of follicular carcinoma with reactivity to thyroglobulin." (PMID 23336429, 2013). "Immunohistochemical marker for FTC is thyroglobulin, which is present in more than 95% of follicular thyroid carcinoma." (PMID 19829820, 2009). "In follicular thyroid carcinoma (FTC), a similar pattern is observed, with thyroglobulin and calcitonin levels showing moderate increases across tumor stages (r = 0.71 and r = 0.62, respectively; p < 0.001)." (PMID 39767732, 2024). "For follicular thyroid carcinoma (FTC), cases positive for BRAF V600E had thyroglobulin levels similar to those observed in PTC (28.5 ± 14.0 ng/mL)." (PMID 39767732, 2024). "Histologically, the tumor had striking follicles with dense, colloid-like material resembling thyroid follicular carcinoma while the tumor cells were negative for thyroid markers (thyroglobulin and thyroid transcription factor-1)." (PMID 28328844, 2017). "Importantly, staining for thyroid transcription factor (TTF-1) and thyroglobulin (Tg) were negative confirming that the tumor was not a metastatic follicular thyroid carcinoma." (PMID 25293503, 2014). "There are also tumors which are considered medullary carcinomas with thyroglobulin immunoreactivity, since they do not fulfill the WHO criteria for “mixed medullary-follicular carcinomas,” it is very difficult to set accurate results." (PMID 24711931, 2014). "Important to exclude in the differential diagnosis are intrathyroidal parathyroid adenoma, follicular thyroid carcinoma (TTF-1 and thyroglobulin positive, PTH negative), and medullary thyroid carcinoma (TTF-1 and calcitonin positive, thyroglobulin and PTH negative)." (PMID 23936709, 2013).
medullary thyroid carcinoma (20 papers, 2008 to 2025). "Comparable artifacts occur, for example, in the thyroid, where some thyroglobulin immunostaining of medullary carcinomas can be observed in areas adjacent to normal follicles that contain abundant thyroglobulin." (PMID 34943588, 2021). "Immunohistochemistry panels have been suggested for suspicious malignancies which include medullary carcinoma (calcitonin, thyroglobulin, CEA, and chromogranin), anaplastic carcinoma (pan-cytokeratin), and metastatic carcinoma (TTF-1)." (PMID 25688327, 2015). "Calcitonin and thyroglobulin are markers for disease recurrence after surgical resection, and the RET point mutations are used to predict susceptibility and prognosis of a patient with familial medullary thyroid cancer." (PMID 24281099, 2010). "However mixed medullary carcinomas are known for thyroglobulin immunopositivity secondary to follicular differentiation." (PMID 18190715, 2008). "Among the discussed biomarkers, thyroglobulin (Tg) and calcitonin (Ctn) hold the greatest clinical importance as the primary markers for differentiated thyroid cancer (DTC) and medullary thyroid cancer (MTC), respectively." (PMID 40507982, 2025). "Immunohistochemistry (ELISON method) showed: in the medullary carcinoma area: PCK (+), CEA (+), CT (focal cytoplasmic weak +), INSM1 (+), Syn (+), CgA (+), Galectin-3 (-), TG (-), CK19 (-), Ki-67 (+, 3%)." (PMID 41323380, 2025). "In our case, cytology of the recurrent lymph node revealed pathological findings of medullary carcinoma, and CEA and calcitonin levels were high and thyroglobulin levels were low in the wash-out fluid from FNA of the recurrent lymph node." (PMID 38647958, 2024). "The demonstration of immunoreactive calcitonin within the neoplastic cells and the lack of thyroglobulin reactivity further support the diagnosis of a pure medullary carcinoma." (PMID 18190715, 2008). "Medullary thyroid carcinoma cells may be spindle-shaped; however, immunohistochemically, they are reactive for keratins, thyroid transcription factor-1 (thyroglobulin-negative), neuron-specific enolase, chromogranin (A, B and C), synaptophysin, opioid peptides and calcitonin." (PMID 24944660, 2014).
type 2 diabetes (18 papers, 2015 to 2026). "Its significant role in secretory tissue makes ERp29 a potential target for treatment of A1AT deficiency, diseases of thyroglobulin processing, and Type 2 Diabetes." (PMID 33013490, 2020). "Single-nucleotide polymorphisms (SNPs) associated with GD, thyroid peroxidase (TPO), thyroglobulin (Tg), thyroid-stimulating hormone (TSH), type 1 diabetes (T1D), and type 2 diabetes (T2D) were obtained from the IEU Open GWAS and FinnGen biobank databases." (PMID 39568808, 2024). "Thyroid parameters, including thyroid-stimulating hormone (TSH), free triiodothyronine (FT3), free thyroxine (FT4), triiodothyronine (T3), thyroxin (T4), thyroid peroxidase antibody (TPOAb), and thyroglobulin antibody (TgAb), of 4136 participants with type 2 diabetes were measured." (PMID 32337292, 2020).
Primary hypothyroidism (16 papers, 2014 to 2026). A type of hypothyroidism that results from a defect in the thyroid gland. "TAI is the predominant cause of primary hypothyroidism resulting from the targeting of thyroid peroxidase (TPO) or thyroglobulin (TG) by autoantibodies, which may ultimately lead to thyroid tissue destruction." (PMID 36589828, 2022). "She developed primary hypothyroidism with elevated antibodies to thyroid peroxidase and thyroglobulin after 25 weeks of treatment, and developed primary adrenal insufficiency with adrenal crisis and fulminant type 1 diabetes with ketoacidosis after 45 weeks." (PMID 38707904, 2024). "A higher prevalence of primary hypothyroidism, anti-microsomal thyroid and anti-thyroglobulin antibodies (Tg-Ab) were reported in workers from a factory producing polyhalogenated biphenyls (PBB) and PBB oxides." (PMID 33114343, 2020). "During his evaluation for SCFE management, primary hypothyroidism was diagnosed due to the presence of anti-thyroid peroxidase and anti-thyroglobulin antibodies." (PMID 28923047, 2017). "Primary hypothyroidism was diagnosed on the basis of a TSH concentration of 2400 mIU/L, with an fT4 concentration of 1 pmol/L, and a thyroglobulin level of 21 μg/L." (PMID 39015673, 2024).